CS (citrate synthase)
Diseases named in the same sentence as CS in open-access papers (continued):
Sharing a sentence is not in itself a finding about the gene and the disease.
tumor (71 papers, 2006 to 2025). "MFO is actually related to a lower CD36 content or lower CS activity, intimately linked to atherosclerotic processes or tumor defense, as well as poorer physical performance." (PMID 35464093, 2022). "CS genes were also overrepresented in genes linked to aging-related diseases, primarily in neoplasms." (PMID 32264951, 2020). "Next we evaluated the effects of R50P and CS mutations on the ability of progerin to inhibit cell growth in the tumor cell line U-2 OS." (PMID 26922519, 2016). "Reduced citrate synthase is proposed to be linked to tumor malignancy via the Warburg effect." (PMID 36835152, 2023). "Furthermore, the loss of citrate synthase results in markedly unregulated glycolysis, decreased citrate production, and accelerated tumor malignancy." (PMID 31141937, 2019). "Pharmacological doses of vitamin C are able to inhibit citrate synthase (CS) activity and reduce the level of glucose-derived citrate, which in turn inhibited tumor proliferation and significantly enhanced the response to gemcitabine." (PMID 40630951, 2025). "Specifically, BRD4, FLT3, and SIAH2 were upregulated in tumor tissues, whereas CS and PIK3CA were downregulated." (PMID 40696656, 2025). "Previous studies have demonstrated that SIRT5 can mediate the desuccinylation of several mitochondrial proteins, such as glutamate dehydrogenase (GDH), malate dehydrogenase, and citrate synthase (CS), which, in turn, affect metabolic processes in tumor cells." (PMID 38256128, 2024). "Lower protein level of pyruvate dehydrogenase and citrate synthase in malignant tumor tissue indicated decreased carbon flux from glucose into the Krebs cycle, whereas the trend was just the opposite in malignant CAAT." (PMID 38247846, 2024). "The results of western blotting showed that NPC tissues had higher levels of CS expression than adjacent non-tumor tissues, which was also supported by immunohistochemical assays." (PMID 38693171, 2024). "In our experiments, CS expression increased in tumor samples, implying the increased activity of enzymes involved in their formation." (PMID 37108213, 2023). "They found that the MI–D compound can effectively enhance the activity of citrate synthase and citric acid and induce tumour metabolic remodelling, and, correspondingly, the tumour-killing effect of the drug is more obvious." (PMID 37108242, 2023). "We further confirmed this correlation by analyzing FASN and CS protein levels in matched normal colon and tumor tissues." (PMID 35742953, 2022). "CS expression: PCa > normal prostate.Decreased CS expression resulted in inhibited PCa proliferation, colony formation, migration, invasion, cell cycle in vitro, and low tumor growth in vivo.CS downregulation lowers lipid metabolism and mitochondrial function." (PMID 35736421, 2022). "There are also several mutations in TCA cycle enzymes associated with tumor proliferation, including mutations in aconitase (ACO2), citrate synthase (CS), succinate dehydrogenase (SDH), fumarate hydratase (FH), and isocitrate dehydrogenase (IDH)." (PMID 33946927, 2021). "In agreement with our proteomic data, we find reduced levels of the CS protein in each of the tumor samples (RB1-6) compared to the controls (Ret1-3)." (PMID 34404904, 2021). "Myomed-205 and -946 also rescued citrate synthase and complex-1 activities in tumor-stressed muscles, possibly suggesting that mitochondrial-metabolic and muscle wasting effects in this CaCax model are mechanistically connected." (PMID 33050629, 2020). "Changes in the expression levels of several TCA cycle enzymes, such as CS and IDH3α,34,35 have also been shown to affect tumour phenotype suggesting that alteration of any step of TCA cycle can be detrimental for cell metabolic homoeostasis." (PMID 31819175, 2020). "We verified that tumor-bearing mice presented lower functional mitochondria as suggested by the lower ATP synthase and citrate synthase activities and OXPHOS subunits levels." (PMID 30602657, 2018).
tumor (continued). "The expression of various mitochondrial enzymes, such as citrate synthase, malic enzyme, malate dehydrogenase, aconitase, and succinate dehydrogenase, control cellular processes involved in tumor formation and cancer cell growth." (PMID 27611801, 2016). "Cortisol is a glucocorticoide and should support neoglucogenesis, but again, citrate synthase is abnormally active in tumor cells and pulls the flux in the glycolytic direction." (PMID 22954255, 2012). "In contrast to the “catabolic hormone situation” tumor cells have an active citrate synthase, pulling the glycolytic flux in the glycolytic direction, to feed the condensation reaction of the Krebs cycle." (PMID 22954255, 2012). "ET also increased LV citrate synthase activity in tumor-bearing animals." (PMID 39838445, 2025). "In addition, GSE29044 had more differentially expressed GRPGs between normal and tumor tissues (CS, PGK1, HNRNPA1, ADPGK, YWHAZ, PTK2, and PGAM1) than GSE42568 (CS, HNRNPA1, ADPGK, and PTK2)." (PMID 40046063, 2025). "Additionally, malignant tumor tissue also displayed lower protein level of CS, the first enzyme in the Krebs cycle." (PMID 38247846, 2024). "Therefore, the inhibition of different types of tumour cells by regulating citrate synthase and its catalytecitric acid has been reported in many studies." (PMID 37108242, 2023). "The gene expression of citrate synthase (CS), related to oxidative metabolism, was similar between tumour-bearing groups (LW = W), and Cox5a gene expression, which is important to maintaining the normal mitochondrial function, was higher in LW in comparison to W group." (PMID 34943780, 2021). "In addition, protein expression of ATP5A and III (ubiquinol-cytochrome c reductase 2 [UQCRC2]) and also the expression of CS were significantly increased, while the expression of Ldha was reduced in the tumour biopsies from the LW group." (PMID 31664147, 2019). "The number of CS type-1 with partial endothelial lining also correlated with ER (γ = −0.622, Z = −3.08, p = 0.002) and PR status (γ = −0.645, Z = −3.12, p = 0.002) and with a presence of tumor emboli in vessels (γ = 0.515, Z = 2.92, p = 0.004)." (PMID 26405632, 2015). "For CS gene, our computational analysis predicted exon B as tumor-specific." (PMID 20813049, 2010). "One tumour tissue displayed only an elevated level of citrate synthase (300%)." (PMID 16404428, 2006). "The upregulation of CS might be responsible for regulating citrate levels and affecting cellular lipid synthesis, which drives key cellular processes such as transformation, tumor development, and disease progression." (PMID 34078919, 2021). "The protein levels of HKII (glycolytic enzyme) and CS (TCA cycle enzyme), as well as HK activity, were similar in tumor and non-tumor cells." (PMID 39195531, 2024). "Both the tumor LDH and CS activities were similar between the groups (p = 0.765, p = 0.123, respectively)." (PMID 38725573, 2024). "Six proteins (LMNA, LCP1, HSPD1, CS, CA1, and ALB) were previously identified as differentially expressed between the tumor center and margin." (PMID 35512017, 2022). "Consistent with previous studies that reported reductions in mitochondrial enzyme activities with cancer cachexia, we found significant reductions in mitochondrial OXPHOS proteins, as well as CS and COX activities, in skeletal muscle of C26 tumor‐bearing mice." (PMID 34427401, 2021). "Recent investigations have shown that citrate, citrate synthase enzyme activity, and SDH are mildly improved in mice‐exposed chemotherapy and C26 tumours." (PMID 33200567, 2020). "While tumor cell switches responding to anabolic hormones: insulin and IGF, support anabolism, powered by oxidative glycolysis that is driven by an active citrate synthase condensation." (PMID 22954255, 2012).
tumor (continued). "Furthermore, by using ST, the study demonstrated significant overexpression of metabolism-related genes (e.g., HK2, PDHA1, and CS) in tumor regions, further supporting the critical role of LSM1 in regulating tumor energy metabolism." (PMID 40867511, 2025). "Moreover, SIRT5 has been proven to affect tumor development by regulating the expression levels of superoxide dismutase 1(SOD1) and citrate synthase (CS)." (PMID 36397343, 2022). "As increased CS and SDH activity would result in an increase in citrate and fumarate, our findings indicating a significant increase in CS and SDH activities in tumor compared to benign mitochondria suggest that this may be worth examining in future studies." (PMID 34078919, 2021). "Immunohistochemical evaluation of IDH2, DNAJA2 and citrate synthase showed diffuse cytoplasmatic staining of both neoplastic and non-neoplastic cells in the tumor microenvironment in both MPN-AITL and R-AITL samples." (PMID 34771688, 2021). "To test this hypothesis, we applied and validated a stable isotope method to measure the ratio of pyruvate dehydrogenase flux to citrate synthase flux (VPDH/VCS, i.e. the percent of total mitochondrial oxidation fueled by glucose) in tumor cells." (PMID 31188872, 2019). "In order to ascertain the adaptation of animals to aerobic physical exercise training, we measured soleus muscle citrate synthase activity in each of the four diet/exercise groups without a tumor burden over the course of 8 weeks." (PMID 31528182, 2019). "In our study, Both CS and ACSS1 gene expression were found increased in HCC tumor tissues." (PMID 27363021, 2016). "In muscle from tumor-free mice, exercise significantly increased the expression of cytochrome c (p = 0.0104), complex III (p = 0.0128), complex IV (p = 0.0012) and COX-IV (p = 0.0244), while complex I, II, V, citrate synthase activity and complex IV activity were unchanged." (PMID 34665826, 2021). "IHC staining of tumor sections was performed to assess the expression levels of metabolism-related enzymes such as the glucose transporter (GLUT1), glyceraldehyde 3-phosphate dehydrogenase (GAPDH), TCA-cycle enzyme citrate synthase (CS), mitochondrial electron transport complex IVc (Comp." (PMID 34200480, 2021). "Interestingly, we found a strong inhibition of CS expression in MRC-5, but not in tumor cells, cultured under hypoxia independent of pH." (PMID 32596143, 2020).
cancer (54 papers, 2011 to 2025). A tumor composed of atypical neoplastic, often pleomorphic cells that invade other tissues. "CS has been reported to be upregulated in a variety of cancers and associated with aggressive progression and poor prognosis." (PMID 37217794, 2023). "Notably, the pattern of evolutionary conservation of CS genes was found to be almost identical to that of cancer-associated genes, apparently reflecting the co-evolution between these two phenomena." (PMID 32264951, 2020). "Furthermore, from yeast to mouse, the pattern of evolutionary conservation of CS genes is almost identical to that of cancer-associated genes, this similarity being the result of the coevolution between these two processes." (PMID 26697428, 2015). "CS genes, LAGs (longevity-associated) and cancer genes could be linked through miRNAs." (PMID 26697428, 2015). "Citrate synthase is involved in the citric acid cycle, and measuring its activity reveals information about mitochondrial function and oxidative metabolism in cancer cells." (PMID 40430171, 2025). "In this study, we used RNA interference (RNAi) to knockdown CS expression in three diverse human cancer cell lines, HCT116, HT-1080, and HepG2, and assessed changes in their cellular behaviors." (PMID 41515967, 2025). "Hypersuccinylation of citrate synthase was, for example, found to suppress cancer cell proliferation and migration." (PMID 40172090, 2025). "Citrate, which is obtained from oxaloacetate and acetyl-CoA by citrate synthase in mitochondria, plays a key role in both normal and cancer cell metabolism." (PMID 38928215, 2024). "Citrate is produced from oxaloacetate (OAA) and acetyl-CoA by citrate synthase (CS) in mitochondria, and it plays a central role in both normal and cancer cell metabolism." (PMID 34205414, 2021). "An interesting result is that while the average expression level and inter-coordination of CS genes increased in all cancer nodules, the expression variability decreased." (PMID 33302383, 2020). "Mutations in genes encoding aconitase, isocitrate dehydrogenase (IDH), succinate dehydrogenase (SDH), fumarate hydratase (FH), and citrate synthase have been observed in many cancer types." (PMID 32252351, 2020). "Recently, we have reported that loss of the respiratory enzyme CS induces an EMT phenotype and alters energy metabolism from aerobic respiration to glycolysis, and results in accelerated cancer cell growth and metastasis." (PMID 29721175, 2018). "The level of VDAC1, a key protein in cancer cell energy and metabolism homeostasis, was also decreased, as were the levels of the Krebs cycle enzyme citrate synthase (CS), the electron transport chain protein complex IV, and ATP synthase subunit 5a." (PMID 29698587, 2018). "It is likely that enhanced CS activity contributes to the conversion of glucose to lipids in cancer by providing substrate for membrane lipid synthesis." (PMID 27363021, 2016). "Our research shows, for the first time, that mtDNA content and citrate synthase activity increase in hyperplastic endometrium compared to control tissues, even if their levels remain lower compared to cancer tissue." (PMID 22676897, 2012). "The role of CS in the development of cancer remains insufficiently explored, and CS may play a dual role in tumorigenesis." (PMID 40557149, 2025). "Since CS knockdown inhibited cell proliferation and stimulated apoptosis, this strategy might be explored to treat such cancers in the future." (PMID 41515967, 2025).
cancer (continued). "Citrate synthase (CS) is a Krebs tricarboxylic acid cycle enzyme that catalyzes citrate synthesis from oxaloacetate and acetyl coenzyme A. CS inactivation facilitates aerobic glycolysis and cancer progression and targeting citrate can be regarded as a novel therapeutic strategy in cancer treatment." (PMID 40046063, 2025). "Similarly, the protein level of CS was increased only in normal-weight women with malignant tumors compared to normal-weight women with benign tumors." (PMID 38247846, 2024). "Moreover, citrate synthase (CS) expression is upregulated in cancer upon metabolic stressful conditions such as hypoxia, favoring the metabolic glutamine reliance." (PMID 32993063, 2020). "REV reduction indicates significant increase of the expression control of CS genes in the cancer cells by the homeostatic mechanisms to confine the fluctuations of the expression levels within narrow intervals, as reported by us in other cancer studies." (PMID 33302383, 2020). "Likewise, AMPK activation level was increased in EIF3F-A549 cancer cells as was the activity of citrate synthase (CS), a marker of mitochondrial capacity in the cell." (PMID 31527668, 2020). "As citrate synthase expression is upregulated in malignant cancer cells and is essential for growth and proliferation, ACC activity may also be high in cancer cells." (PMID 31027222, 2019). "On the one hand, increased CS activity, by providing more citrate, could be an advantage for cancer cells that depend on increased fatty acid biosynthesis, such as pancreatic cancer." (PMID 25057353, 2014). "MtDNA content and citrate synthase activity increases in pre-malignant lesions could be a potential molecular marker for progression from hyperplasia to carcinoma." (PMID 22676897, 2012). "Interestingly, the loss of CS was linked to the induction of the epithelial-to-mesenchymal transition (EMT), suggesting that CS deficiency not only promotes a metabolic rewiring but also indirectly supports cancer cell invasion and metastasis." (PMID 25057353, 2014). "Citrate synthase (CS) is a key rate-limiting enzyme in the tricarboxylic acid (TCA) cycle and plays a crucial role in cancer progression." (PMID 40557149, 2025). "This study investigated the cellular and gene expression changes in three human cancer cell lines, HCT116, HT-1080, and HepG2, upon RNAi-mediated knockdown of CS expression." (PMID 41515967, 2025). "While malignant tumor tissue showed lower protein levels of PDH, CS, and PDK4 in both normal-weight and obese women, CAAT showed an increase in the protein levels of the same enzymes with the exception of PDH in normal-weight women." (PMID 38247846, 2024). "The results showed that the expression levels of LDHA, CS, IDH3G were significantly higher in cancer tissues than those in normal tissues." (PMID 36229828, 2022). "For example, altered expression of citrate synthase (CS), aconitase (ACO2) and malate dehydrogenase (MDH2) has been reported to contribute to cancer-specific features, such as glycolysis addiction, resistance to chemotherapy and increased lipid biosynthesis." (PMID 30668541, 2019). "The genes ACLY, CS, RPE, and IDH2 were found to be among the top 10% of the genes that were frequently overexpressed across 19 cancer types from a meta-analysis study of 1981 tumors (FDR p value < 0.05)." (PMID 30823893, 2019). "We found that in the first three steps of the TCA cycle, digital expression of aconitase 2 (ACO2) in the brain exceeded both citrate synthase (CS) and isocitrate dehydrogenase 2 (IDH2), while in cancer cells this trend was quite the opposite." (PMID 22166000, 2011). "As the effects of CS knockdown have been controversial in SKOV3, A2780, HeLa, SF188, and 293T cells, we decided to look more closely at the roles of CS in three popular and diverse human cancer cell lines: HCT116, HT-1080, and HepG2." (PMID 41515967, 2025).
cancer (continued). "In absence of extracellular citrate, cancer cells employ different mechanisms to support mitochondrial Citrate Synthase (CS) activity and, in turn, increased citrate synthesis." (PMID 38425123, 2024). "No CS mutations have been reported to reside in the CSB-WHD, however analysis of cancer genomics databases of both BioPortal and COSMIC revealed the presence of somatic mutations in the CSB-WHD." (PMID 33806087, 2021). "In addition to ACSS, citrate synthase (CS), the first TCA cycle enzyme, is another potential target for cancer therapy." (PMID 27363021, 2016). "No statistically significant change in mtDNA content and CS activity was found in cancer progression (data not shown)." (PMID 22676897, 2012). "Moreover, in aggressive cancer cells, it is not infrequent to observe the upregulation of mitochondrial enzymes, such as CS, or mitochondrial transporters, such as some translocases of the inner and outer mitochondrial membrane (TIMM and TOMM)." (PMID 34205414, 2021). "Along with the protein expression levels shown by Western blotting, the enzymatic activities of CS (representatives of the tricarboxylic acid cycle) and COX (representatives of the electron transport chain), which are indicators of mitochondrial content, were also decreased with cancer cachexia." (PMID 34427401, 2021). "Importantly, the enzyme activity of both CS and ACSS1 have been reported to be increased in HCC and these two enzymes catalyze the reactions that provide alternative sources of energy and substrates for multiple rapid proliferating cancer cells including HCC cells." (PMID 27363021, 2016).